TUBD1 (tubulin delta 1)
Description:
Acts as a positive regulator of hedgehog signaling and regulates ciliary function.
Synonyms: TUBD; FLJ12709
Tractability: Small molecule: it belongs to a druggable protein family. PROTAC: ubiquitination databases record sites on it.
Gene: Protein-coding gene on chromosome 17 (59,859,426 to 59,892,945, reverse strand). Ensembl gene ENSG00000108423.
Subcellular location: Nucleus; Cytoplasm; Cytoplasm, cytoskeleton, microtubule organizing center, centrosome, centriole; Cell projection, cilium
Subcellular location (Human Protein Atlas): Cytosol; Nucleoplasm
Gene Ontology:
Molecular function: protein binding; GTP binding; structural constituent of cytoskeleton
Biological process: cytoskeleton organization; microtubule cytoskeleton organization; mitotic cell cycle; positive regulation of smoothened signaling pathway; microtubule-based process
Cellular component: centrosome; centriole; cytoplasm; nucleus; cilium; microtubule; microtubule cytoskeleton
Genetic constraint (gnomAD): Loss-of-function variants: 34 observed, 47.67 expected, observed/expected ratio (o/e) 0.71, 90% interval 0.54 to 0.95. The upper end of that interval is the gene's LOEUF score, 0.95, which puts it in group 4 of 6, group 1 being the genes least tolerant of losing a copy. Missense variants: 477 observed, 554.82 expected, observed/expected ratio (o/e) 0.86, 90% interval 0.8 to 0.93. Synonymous variants: 167 observed, 184.85 expected, observed/expected ratio (o/e) 0.9, 90% interval 0.8 to 1.03.
Homologues: Orthologues: chimpanzee TUBD1 (99% identical), macaque TUBD1 (96% identical), pig TUBD1 (90% identical), dog TUBD1 (90% identical), rabbit TUBD1 (88% identical), guinea pig TUBD1 (86% identical), mouse Tubd1 (86% identical), rat Tubd1 (85% identical), tropical clawed frog tubd1 (70% identical), zebrafish tubd1 (60% identical). Paralogues in human: TUBB4B (27% identical), TUBB8 (27% identical), TUBB2A (27% identical), TUBB2B (27% identical), TUBE1 (27% identical), TUBB8B (26% identical), TUBB4A (26% identical), TUBB (26% identical), TUBB3 (26% identical), TUBB6 (25% identical), TUBB1 (25% identical), TUBA3C (24% identical), and 11 more.
Diseases named in the same sentence as TUBD1 in open-access papers:
TUBD1 is named in the same sentence as 8 diseases in open-access papers, as found by Europe PMC text mining. Sharing a sentence is not in itself a finding about the gene and the disease. The quoted sentences say what the papers report.
breast tumours (1 paper, 2007). "Finally, our data revealed seven other protein coding genes (FAM33A, DHX40, CLTC, PTRH2, TMEM49, TUBD1, ABC1, and USP32) that have not been implicated previously in 17q23 studies, but whose expression was clearly associated with copy number status in primary breast tumours." (PMID 17353917, 2007).
pulpitis (1 paper, 2025). Inflammation of the dental pulp. "For the phenotype Pulpal and apical diseases, two other loci in chromosomes 2 (near BCL11A) and 9 (near RMI1), and for the phenotype Pulpitis, three other loci in chromosomes 1 (near PDE4B), 9 (near NR4A3), and 17 (near VMP1 and TUBD1) were identified." (PMID 40701953, 2025).
tumor (4 papers, 2007 to 2024). "In addition, γ-synuclein affects centrosome components γ-tubulin (TUBG1) and Δ-tubulin (TUBD1) which are associated with tumorigenesis and tumor progression." (PMID 24040069, 2013).
infection (1 paper, 2017). The state of being infected such as from the introduction of a foreign agent such as serum, vaccine, antigenic substance or organism. "In addition, the downregulation of TUBD1 and microfilament-associated protein CNN3 associated with the cytoskeleton was detected in DT40 cells following vvIBDV infection, as also observed in CEF cells." (PMID 28086922, 2017).
proliferative retinopathy (1 paper, 2022). "The absence of coexpression of TUBD1 a and b (Vab) isoforms is significantly associated with the risk of developing DR, specifically proliferative retinopathy, whereas the coexpression of TUBD1 isoforms a, b, and d (Vabd) has been associated with risk for developing nonproliferative retinopathy." (PMID 35308095, 2022).
TUBD1 also shares sentences with these, for which no sentence is quoted: endometrial cancer (1 paper); esophageal squamous cell carcinoma (1); pancreatic cancer (1).